DRC3 (dynein regulatory complex subunit 3)
Description:
Component of the nexin-dynein regulatory complex (N-DRC) a key regulator of ciliary/flagellar motility which maintains the alignment and integrity of the distal axoneme and regulates microtubule sliding in motile axonemes.
Synonyms: LRRC48; DKFZP586M1120; CFAP134
Tractability: Small molecule: a structure with a bound ligand is known. PROTAC: ubiquitination databases record sites on it.
Gene: Protein-coding gene on chromosome 17 (17,972,813 to 18,016,889, forward strand). Ensembl gene ENSG00000171962.
Subcellular location: Cytoplasm, cytoskeleton, cilium axoneme; Cell projection, cilium; Cytoplasm, cytoskeleton, flagellum axoneme; Cell projection, cilium, flagellum
Subcellular location (Human Protein Atlas): End piece; Mid piece; Principal piece
Gene Ontology:
Molecular function: protein binding
Biological process: cilium movement; flagellated sperm motility
Cellular component: axoneme; cytoplasm; axonemal nexin link; cilium; sperm flagellum; axonemal doublet microtubule; motile cilium
Genetic constraint (gnomAD): Loss-of-function variants: 39 observed, 48.22 expected, observed/expected ratio (o/e) 0.81, 90% interval 0.62 to 1.06. The upper end of that interval is the gene's LOEUF score, 1.06, which puts it in group 4 of 6, group 1 being the genes least tolerant of losing a copy. Missense variants: 573 observed, 609.35 expected, observed/expected ratio (o/e) 0.94, 90% interval 0.88 to 1.01. Synonymous variants: 229 observed, 249.65 expected, observed/expected ratio (o/e) 0.92, 90% interval 0.82 to 1.02.
Homologues: Orthologues: chimpanzee DRC3 (98% identical), macaque DRC3 (93% identical), guinea pig DRC3 (84% identical), dog DRC3 (83% identical), mouse Drc3 (81% identical), rat Drc3 (80% identical), pig DRC3 (77% identical), tropical clawed frog drc3 (58% identical), zebrafish drc3 (49% identical), Drosophila melanogaster Ppr-Y (33% identical), Drosophila melanogaster TbCMF46 (32% identical). Paralogues in human: LRRC9 (20% identical), CEP97 (17% identical), LRGUK (17% identical), LRRCC1 (17% identical), DNAAF1 (16% identical), DNAAF11 (15% identical), LRRC49 (15% identical), LRRC43 (14% identical), LRRIQ3 (11% identical), PPP1R42 (11% identical), LRRC46 (10% identical), LRRC23 (10% identical), and 1 more.
Diseases named in the same sentence as DRC3 in open-access papers:
DRC3 is named in the same sentence as 7 diseases in open-access papers, as found by Europe PMC text mining. Sharing a sentence is not in itself a finding about the gene and the disease.
DRC3 shares sentences with these, for which no sentence is quoted: Hydrocephalus (4 papers); breast carcinoma (2); asthma (1); colorectal cancer (1); male infertility (1); prostate carcinoma (1); sinusitis (1).